HGF (hepatocyte growth factor)
Diseases named in the same sentence as HGF in open-access papers (continued):
Sharing a sentence is not in itself a finding about the gene and the disease.
tumor (continued). "HGF/c-Met coexpression is often strongest at the infiltrative margins of tumours." (PMID 25887320, 2015). "It was found that neither higher baseline nor elevation of HGF levels upon treatment was associated with baseline tumor burden, number of liver metastases, tumor response, or stage of the tumor at diagnosis." (PMID 28536405, 2015). "The tumor size in HGF group was significantly bigger than that in control group." (PMID 26115510, 2015). "In addition to HGF and MET overexpression, this pathway can also be activated through genetic alterations such as MET-activating mutations that, although rare in all tumor types, are certainly contributing to carcinogenesis." (PMID 26319934, 2015). "It seems that, in these cases, a greater concentration of HGF and/or proximal interaction of tumor and stromal cells are critical for the activation of the MET pathway (although HGF measurements include the stromal pool, and thus they do not necessarily equate with its active form)." (PMID 26319934, 2015). "Furthermore, numerous studies have suggested that MACC1 induces tumor metastasis through the regulation of the hepatocyte growth factor (HGF)/MET signaling pathway." (PMID 26043756, 2015). "However, it is also possible that the tumor cells themselves produce HGF, enabling cMET signaling in an autocrine way." (PMID 25815459, 2015). "The major pancreatic elastase-generated fragment (termed NK4 because it contains HGF’s N-terminal domain and all 4 kringle domains), has anti-tumor and anti-angiogenic activity in mice when directly injected or when generated by infection with an NK4-expressing adenoviral vector." (PMID 25938594, 2015). "Because HGF is one of the key soluble factors produced by tumor cells as well as stromal cells in PDAC, we tested whether the activity of HGF could be increased in the presence of CS-E." (PMID 26642349, 2015). "Interestingly, the same study reported massive tumour regression with miR-34a plus gefitinib in mouse xenograft models of HGF-induced gefitinib-resistant tumours." (PMID 26435742, 2015). "By addition of crizotinib to canertinib treatment, HGF-driven rescue could be overcome and tumor cell survival was disrupted." (PMID 25799134, 2015). "The elevation of HGFA and reduction of HAIs have been reported in a variety of tumors, indicating that the disruption of the balance between HGF activation and inhibition may favor tumor formation." (PMID 28536405, 2015). "Indeed, HGF is a well-recognized proangiogenic mediator which inhibition reduces tumor growth and metastasis, as well HIF-1α, which is associated with poor prognosis in cancer due stimulation of VEGFR+ cells migration to the tumor." (PMID 26099922, 2015). "Indeed, overexpression of wild-type c-Met or engagement by HGF in an autocrine or paracrine fashion induces tumor transformation." (PMID 25895026, 2015). "Two recent reports show that both IL-6-Stat3 and HGF-Met oncogenic signaling pathways are negatively regulated by miR-26a in HCCs, suggesting that downregulation of miR-26a promotes proliferation, migration and invasion of tumor cells in vitro and in vivo." (PMID 25537511, 2015). "Similarly for HGF, deregulated HGF/MET signaling is a common hallmark of many tumors and is associated with various aspects of tumor progression." (PMID 26100469, 2015). "However, the mean percentage (27%) of tumor volume reduction in the HGF-treated tumors was obviously less than that of the control (62.7%), HGF+PI3K inhibitor (48.3%) and HGF+GRP78 inhibitor-treated tumors (45.8%)." (PMID 26115510, 2015). "It remains unclear why the transmigration of Met+ neutrophils in vivo was dependent on HGF produced in the tumor environment when these neutrophils could potentially respond to other chemotactic cues recruiting Met-negative neutrophils." (PMID 26438048, 2015).
tumor (continued). "Indeed, the cytokines HGF, osteopontin, and stromal-derived factor 1α (SDF-1) secreted from tumor-associated cells increase CD44v6 expression in CR-CSCs by activating the Wnt/β-catenin pathway which promotes migration and metastasis." (PMID 28536400, 2015). "The phenomenon of HGF/MET-induced bypass is in line with previous reports in other tumor types." (PMID 26496080, 2015). "The information presented indicates that circulating HGF and MET levels, MET protein expression levels in tumor tissues, and MET gene amplification, copy number and mutation, as well as markers related to crosstalk of related pathways, are commonly evaluated biomarkers." (PMID 28536405, 2015). "This review aims to highlight the role of HGF in tumor formation, progression, and metastasis." (PMID 28536400, 2015). "Since we previously reported that HS20 could reduce HCC tumor growth by inhibiting Wnt signaling, both the Wnt and HGF signaling pathways could play a role in HS20’s inhibitory effect." (PMID 26332121, 2015). "Furthermore, HGF plays a definitive role in both intrinsic and acquired resistance to anti-tumor drug by increasing the PI3K/AKT signaling, an important survival pathway in NSCLC." (PMID 26115510, 2015). "We previously reported that selective MET inhibitors may specifically inhibit HGF-autocrine GBM tumor growth." (PMID 26381735, 2015). "Therefore, functional HGF to activate c-Met was reasonably postulated to be secreted from not only CAFs and other inflammatory processes but also tumor cells, although further investigations for clarification is needed." (PMID 26036285, 2015). "Additionally, focus beyond the molecular pathway’s direct consequences to include the tumor microenvironment and downstream effects on tumor behavior continue to keep HGF at the forefront of research focused on neoplastic invasion." (PMID 26404380, 2015). "To determine whether MET overexpression or mutation was sufficient to induce tumor formation and invasion in-vivo, we established tumor xenograft models in human HGF transgenic mice on a severe combined immunodeficiency (SCID) background, named hHGF Tg SCID." (PMID 25605252, 2015). "In addition, increased HGF expression was significantly correlated with tumor differentiation, tumor depth, lymph node metastasis, and pathological stage." (PMID 26036285, 2015). "Therefore, we investigated the alleged contribution to the fibroblast-mediated increase in cancer cell migration speed of three CAF-released growth factors which are believed to greatly influence tumor spread, such as HGF, TGF-β or bFGF." (PMID 25880005, 2015). "The change in basal phosphorylation status and reduced responsiveness in the 3D cultures may be linked to the change in cell proliferative response to EGF and HGF in the tumor spheroids." (PMID 24638075, 2014). "Thus, HGF-dependent Met activation has emerged as an attractive target for therapeutic intervention because of its role in promoting tumor cell EMT, angiogenesis, proliferation and survival." (PMID 26932375, 2014). "Studies in larger cohorts of MPN patients are needed to validate that the HGF level in serum reflects the tumour burden, and thus could be used as a prognostic marker." (PMID 25119536, 2014). "DN-30 Fab (also called monovalent DN-30, MvDN30) reduces the anchorage-independent growth of a broad panel of HGF-dependent or -independent tumor cells, and induces growth arrest and apoptosis of tumor cells addicted to MET signaling in in vitro proliferation assays." (PMID 28548076, 2014). "Moreover, it was emphasized that HGF staining was present in a small fraction of tumor cells located at the invading front of the tumor and was colocalized with PTC cells characterized by enhanced expression of Met protein." (PMID 28548071, 2014).
tumor (continued). "Based on the close involvement of HGF and its receptor Met—not only in tumor development, invasion, and metastasis but also in resistance to anticancer therapies—drug discovery targeting the HGF–Met pathway has become a hot target in anticancer drug development." (PMID 28548072, 2014). "It seems possible that HGF/Met interactions in the leading front of the tumor may have a major role in favoring invasiveness." (PMID 28548071, 2014). "Ras inhibition by FTS reduced the ATP steady state but FTS treatment did not by itself affect tumor blood volume; however, it abolished the HGF/SF-induced increase in tumor blood volume, and it did this despite the increase in glucose uptake shown here to be induced by FTS." (PMID 25593982, 2014). "Overexpression of HGF can also induce oncogenic effects through over-stimulation of the non-mutated Met receptor, which can lead to enhanced tumor cell progression and malignant phenotype." (PMID 26932375, 2014). "This enhanced tumor-growth phenotype was abrogated by the administration of HGF (hepatocyte growth factor) inhibitor, suggesting that the pro-tumorigenic effect of pks+ E. coli-induced senescent cells is mainly mediated by HGF." (PMID 25256712, 2014). "In HER2 amplified GEC cell lines, HGF-mediated MET activation is able to rescue tumor cells from EGFR/HER2 inhibition, an effect that could be abrogated by knockdown or pharmacologic inhibition of MET." (PMID 24930887, 2014). "HGF stimulation of PTC cells causes prompt phosphorylation of Met protein, stimulates the migratory/invasive capacity of tumor cells, up-regulates the expression of the pro-invasive molecule cyclo-oxygenase 2, and down-regulates the anti-metastatic protein KAI-1/CD82." (PMID 28548071, 2014). "In the presence of MVs, there was a marked intensification of HGF staining on tumor sections." (PMID 24797571, 2014). "In addition, several reports have shown that tumor growth and invasion by UC is inhibited by regulation of the HGF-Met signaling system." (PMID 25521854, 2014). "Although these findings suggest that tocotrienol treatment can also act to suppress the compensatory mechanisms that promote tumor growth and survival during hypoxic conditions, possibly through the inhibition of HGF/Met activation, additional studies are required to establish a direct relationship." (PMID 26932375, 2014). "Similarly, tumor cells transfection with Met specific siRNA significantly inhibits HGF-dependent growth." (PMID 26932375, 2014). "We showed that FTS inhibits the increase in tumor blood flow induced by HGF/SF-Met activation." (PMID 25593982, 2014). "Increased local concentrations of HGF in the spheroid may also be leading to autocrine/paracrine effects, as it has been shown that HGF is secreted by tumor cells and could lead to phosphorylation of cMET." (PMID 24638075, 2014). "In light of this work, if disseminated tumor cells could persist in mammary gland, they could support recurrence after fat grafts, under the influence of ASCs through the activation of HGF/c-Met/beta-catenin axis." (PMID 24327602, 2014). "However, in rare cases, tumor cells can express HGF, leading to an autocrine loop-type mechanism of activation of MET." (PMID 24930887, 2014). "In the cancer setting, c-Met/HGF mediates cellular proliferation, tumor invasion, and metastasis." (PMID 25256830, 2014). "However, these biological actions that are driven by the HGF–Met pathway all play a role in the acquisition of the malignant characteristics in tumor cells—invasion, metastasis, and drug resistance in the tumor microenvironment." (PMID 28548072, 2014). "So in LX2 cocultured induced sorafenib resistance in Huh7, LX2 secreted HGF into the tumor microenvironment which activated HGF/c-Met axis and thus activates p-Akt and then reactivated p-ERK somehow which finally led to the increased level of antiapoptotic protein and decreased caspase cleavage." (PMID 25057499, 2014).
tumor (continued). "Moreover, the higher dose of FTS used in this study led to the inhibition of blood volume in the tumor following HGF/SF administration, demonstrating the potency of the inhibitor." (PMID 25593982, 2014). "Moreover, it revealed able to regulate beta-catenin localization suggesting an additional role of the HGF/c-Met mediated crosstalk in tumor self-renewal, via regulation of cells subpopulation endowed with stem-like properties." (PMID 24327602, 2014). "Dysregulation of the Hepatocyte growth factor (HGF)/c-Met signaling axis upregulates diverse tumor cell functions, including cell proliferation, survival, scattering and motility, epithelial-to-mesenchymal transition (EMT), angiogenesis, invasion, and metastasis." (PMID 24849787, 2014). "Generally, the paracrine signaling pathway of HGF is the major cause of c-Met expression, as not all tumor cells produce HGF." (PMID 25202379, 2014). "Inhibitory effect of HGF on tumor anoikis is abolished by tetraspanin CD151 deletion." (PMID 23296269, 2013). "Since overexpression of HGF has been associated with poor clinical outcome in OVCA, we evaluated the expression of c-Met, the only known HGF receptor, in OVCA cells and primary OVCA tumor samples." (PMID 23467907, 2013). "HGF-induced Snail expression not only suppresses E-cadherin expression, but also promotes epithelial-mesenchymal transition, a process that allows epithelial cells to gain a fibroblast-like phenotype that is essential for tumor invasion." (PMID 24287743, 2013). "Erlotinib treatment markedly inhibited tumor cell proliferation and angiogenesis in PC-9/Vec xenografts, whereas erlotinib did not affect cell proliferation or angiogenesis significantly in PC-9/HGF xenografts." (PMID 23690929, 2013). "Regardless of the presence or absence of MET mutation, stroma-secreted HGF plays a common role in tumor invasive growth." (PMID 23296269, 2013). "Since activation of these kinases leads to the cellular proliferation, angiogenesis, and anti-apoptotic effects, these results now provide new insights into how HGF may affect tumor growth and angiogenesis." (PMID 24023761, 2013). "Moreover, since HGF confers resistance to targeted drugs in several tumor types, clinical trials of mTOR inhibitors are warranted." (PMID 23690929, 2013). "Likewise, local expression of HGF-transgene via an organ-specific gene promoter led to a higher incidence of tumor formation in muscles, airways, skin and mammary glands." (PMID 23296269, 2013). "Furthermore, we showed that HGF overexpression is present in tumors from Japanese patients with acquired and intrinsic tumor resistance to EGFR-TKI at frequencies of about 60% and 30%, respectively." (PMID 23690929, 2013). "Moreover, HGF/SF was shown to be able to enhance the metastatic potential of NPC tumor cells that express Met." (PMID 24340011, 2013). "The HGF/c-Met signaling pathway plays a key role in tumorigenesis and tumor progression." (PMID 23877345, 2013). "Many of them such as SDF-1, HGF/SF or S1P may be upregulated in tumor cells and microenvironment (e.g., ascites) in response to chemo/radiotherapy." (PMID 24373588, 2013). "HGF/cMET axis may regulate the expression of E-cadherin, N-cadherin, and extracellular matrix degrading proteases, thus facilitating the invasiveness of tumor cells." (PMID 24005867, 2013). "In particular, additional research is warranted to evaluate the impact of HGF therapy in anti-tumor immunity as the potent immune inhibition exerted by HGF may help tumor cells to escape from immune surveillance." (PMID 24344806, 2013). "Stroma-derived HGF is responsible for tumor invasive growth." (PMID 23296269, 2013). "Like NK4, anti-HGF antibody suppresses tumor progression in rodents." (PMID 23296269, 2013). "Moreover, blood leukocytes inhibit anoikis and enhance SDF1 signaling in tumor cells during blood flow via a secretion of HGF into blood (i.e., endocrine system)." (PMID 23296269, 2013).
tumor (continued). "Tumor HGF–MET axis is now critical for drug resistance and cancer stem cell maintenance." (PMID 23296269, 2013). "HGF–MET cascade also participates in anti-tumor drug resistance, possibly through CSC conversion." (PMID 23296269, 2013). "HGF was elevated in the plasma of HFD-E tumor-bearing mice, and may play a role in driving HFD-E tumor growth." (PMID 24156623, 2013). "Given that tumor-stroma interaction via HGF–MET axis is involved in cancer metastasis, inhibition of MET signaling may be a pathogenesis-based anti-tumor strategy." (PMID 23296269, 2013). "Hematogenous dissemination is the most common route for cancer metastasis, but the role of HGF and c-Met in circulating tumor cells (CTCs) is unknown." (PMID 23723997, 2013). "It was interesting that the tendency of HGF production was consistent with that of tumor volume growth, which led to the hypothesis that HGF played a mediator role in HCC proliferation facilitated by H-CAFs." (PMID 23667593, 2013). "Indeed, NK4-like fragments are detectable in the culture supernatants of certain tumor cell lines that produce HGF." (PMID 23296269, 2013). "Concomitantly, significant temporal upregulation in hypoxia and the pro-angiogenic growth factors hypoxia-inducible factor 1-alpha, hepatocyte growth factor, vascular endothelial growth factor and transforming growth factor-beta were seen within the surviving tumor." (PMID 24403226, 2013). "In SV40-transfected human ECs (SV1 cells), endocan regulates HGF/SF-mediated mitogenic activity and may support the function of HGF/SF, not only in embryogenesis and tissue repair after injury but also in tumor progression." (PMID 24171112, 2013). "This is the first proof of concept to show that HGF-antagonist is useful for anti-tumor therapy." (PMID 23296269, 2013). "Although small-sized TK inhibitors facilitate an oral administration (i.e., systemic exposure), an effective dose might impair non-tumor normal organs, since endogenous HGF is essential for organ homeostasis." (PMID 23296269, 2013). "HGF, which is released by CAFs, promotes tumour cell migration and invasion." (PMID 24216702, 2013). "We previously reported that, in NSCLC patients, HGF is present mainly in cancer cells with acquired resistance to EGFR-TKIs, suggesting that HGF may be produced predominantly in resistant tumor cells via an autocrine mechanism." (PMID 24386407, 2013). "During EMT, tumor cells acquire HGF-transcriptional activity (i.e., autocrine mechanism)." (PMID 23296269, 2013). "Moreover, HGF can affect tumor malignancy by inhibiting basal and radio-/chemotherapy-induced tumor cell death and apoptosis." (PMID 22741575, 2012). "Furthermore, we co-cultured HGF-secreting fibroblasts with Met-expressing cancer cells to mimic the paracrine HGF/Met pathway, which is active in the tumor microenvironment." (PMID 22788954, 2012). "Moreover, also the DN30 ability to inhibit HGF-dependent tumor cell scattering and invasiveness in vitro was shown to depend on ADAM-10." (PMID 22973229, 2012). "HGF retained the ability to recover ErbB2 tumor cells treated with Iressa and Tarceva." (PMID 23028720, 2012). "HGF might influence tumor progression by modulating the cell growth, migration and chemoresistance to drugs." (PMID 22741575, 2012). "Inhibition of HGF or c-Met expression leads to suppression of in vivo tumor formation and growth." (PMID 22741575, 2012). "The tumor microenviroment can secrete growth factors such as hepatocyte growth factor (HGF) which results in activation of the HGF receptor MET and subsequent downstream Raf/MEK/ERK and PI3K/PTEN/Akt/mTOR signaling which results in resistance to the small molecule inhibitors." (PMID 23085539, 2012). "The same research group obtained similar results in a preclinical model into immunocompromised mice: they found a therapeutic window wherein HGF, with a paracrine/autocrine action, sensitises tumours to low doses of CDDP and PTX, which are otherwise ineffective." (PMID 22999213, 2012).